PCDHGB3 (protocadherin gamma subfamily B, 3)
Description:
Potential calcium-dependent cell-adhesion protein. May be involved in the establishment and maintenance of specific neuronal connections in the brain.
Synonyms: PCDH-gamma-B3
Tractability: Antibody: UniProt places it where antibodies can reach, with medium confidence; UniProt predicts a signal peptide or a membrane-spanning region; its Gene Ontology location is reachable by antibodies, with medium confidence; the Human Protein Atlas places it where antibodies can reach.
Gene: Protein-coding gene on chromosome 5 (141,370,242 to 141,512,975, forward strand). Ensembl gene ENSG00000262209.
Subcellular location: Cell membrane
Subcellular location (Human Protein Atlas): Plasma membrane; Cytosol; Nucleoplasm; Vesicles
Gene Ontology:
Molecular function: cell adhesion molecule binding; calcium ion binding
Biological process: cell adhesion; homophilic cell-cell adhesion
Cellular component: plasma membrane; membrane
Genetic constraint (gnomAD): Loss-of-function variants: 40 observed, 62.48 expected, observed/expected ratio (o/e) 0.64, 90% interval 0.5 to 0.83. The upper end of that interval is the gene's LOEUF score, 0.83, which puts it in group 3 of 6, group 1 being the genes least tolerant of losing a copy. Missense variants: 1,309 observed, 1,267.6 expected, observed/expected ratio (o/e) 1.03, 90% interval 0.99 to 1.08. Synonymous variants: 581 observed, 541.61 expected, observed/expected ratio (o/e) 1.07, 90% interval 1 to 1.15.
Homologues: Paralogues in human: PCDHGB1 (71% identical), PCDHGB2 (71% identical), PCDHGB5 (70% identical), PCDHGB4 (69% identical), PCDHGB6 (67% identical), PCDHGB7 (67% identical), PCDHGA5 (51% identical), PCDHGA12 (51% identical), PCDHGA1 (50% identical), PCDHGA6 (50% identical), PCDHGA11 (50% identical), PCDHGA7 (50% identical), and 49 more.
Diseases named in the same sentence as PCDHGB3 in open-access papers:
PCDHGB3 is named in the same sentence as 1 disease in open-access papers, as found by Europe PMC text mining. Sharing a sentence is not in itself a finding about the gene and the disease. The quoted sentences say what the papers report.
cervical cancer (1 paper, 2022). A primary or metastatic malignant neoplasm involving the cervix. "Most of the PCDHG family (e.g. PCDHGB3 and PCDHGA6) are calcium-dependent cell-adhesion proteins, significantly mutated in SC1 patients and previously reported as diagnostic markers for cervical cancer." (PMID 35439935, 2022).